ENSG00000288708 (novel protein)
Synonyms: LOC127903862
Gene: Protein-coding gene on chromosome 6 (16,328,342 to 16,328,431, reverse strand). Ensembl gene ENSG00000288708.
Genetic constraint (gnomAD): Loss-of-function variants: 1 observed, 1.46 expected, observed/expected ratio (o/e) 0.68, 90% interval 0.21 to 1.84. That is too few expected variants to judge how well the gene tolerates losing a copy. Missense variants: 31 observed, 30.76 expected, observed/expected ratio (o/e) 1.01, 90% interval 0.76 to 1.36. Synonymous variants: 17 observed, 11.91 expected, observed/expected ratio (o/e) 1.43, 90% interval 0.96 to 1.9.